KLF2 (KLF transcription factor 2)
Diseases named in the same sentence as KLF2 in open-access papers (continued):
Sharing a sentence is not in itself a finding about the gene and the disease.
endothelial dysfunction (continued). "KLF-2 plays a key role in the formation of hepatic fibrosis and endothelial dysfunction as it is endogenously expressed early in the development of cirrhosis in response to vascular dysfunction." (PMID 36300180, 2022). "In cirrhotic livers, SV enhanced KLF2-dependent vasoprotective mechanisms, thereby preventing liver damage, inflammation and oxidative stress and improving endothelial dysfunction." (PMID 35277075, 2022). "The reduced expression level of KLF2 (Krüppel-like factor 2), an essential regulator of endothelial functions, also was found to be closely related to hyperglycaemia-induced endothelial dysfunction." (PMID 34445477, 2021). "Further experiments determining the role of KLF2 in COVID-19-induced endothelial dysfunction in vivo is warranted." (PMID 34253708, 2021). "In our future study, the direct or indirect interaction between Azilsartan and KLF2 will be further investigated to better understand the functional mechanism of Azilsartan on endothelial dysfunction and thereafter on cardiovascular diseases." (PMID 33946046, 2021). "In our study, we observed that KLF2 was downregulated by COVID-19 patient serum, which provides a novel mechanism of KLF2 in suppressing endothelial dysfunction in COVID-19." (PMID 34253708, 2021). "In conclusion, the present study uncovers KLF2 downregulation as an important mechanism driving COVID-19-induced endothelial dysfunction as well as underscoring the importance of examining endothelial function in COVID-19 patients." (PMID 34253708, 2021). "Loss of nuclear localisation as well as anti-inflammatory and anti-proliferative properties of p.H288Y KLF2 mutant suggests that this genetic modification is likely to exacerbate endothelial dysfunction in patients." (PMID 32132543, 2020). "In addition, KLF2 has anti‐inflammatory and antioxidant effects, preventing the progression and development of endothelial dysfunction." (PMID 39092773, 2024). "Furthermore, KLF2 expression in monocytes and endothelial cells was reduced in COVID‐19 patients due to the development of endothelial dysfunction, and KLF2 activators like atorvastatin ameliorated endothelial dysfunction in COVID‐19 patients." (PMID 39092773, 2024). "Reduced KLF2 expression may contribute to endothelial dysfunction and barrier disruption following SCI." (PMID 36632224, 2023). "KLF2 has been evaluated as a therapeutic target for COVID-19-induced endothelial dysfunction." (PMID 37243274, 2023). "To measure endothelial dysfunction, we documented decreased production of eNOS and KLF2, a zinc finger family of transcription factors and bona-fide master regulator of endothelial maintenance function, and increased levels of endothelial cell surface von-Willebrand Factor." (PMID 35355507, 2022). "Taken together, our data show that Azilsartan might ameliorate ox-LDL-induced endothelial dysfunction via elevating the expression of KLF2." (PMID 33946046, 2021). "The changes in KLF2 and vWF expression are indicative of endothelial dysfunction and may perpetuate vascular inflammation and coagulation." (PMID 34935423, 2021). "The objective of the present study is to evaluate whether kruppel-like factor 2 (KLF2), a master regulator of vascular homeostasis, represents a therapeutic target for COVID-19-induced endothelial dysfunction." (PMID 34253708, 2021). "Kruppel-like factor 2 (KLF2) is involved in endothelial dysfunction induced by high glucose." (PMID 34177809, 2021). "To demonstrate whether KLF2 plays an important role in COVID-19-induced endothelial dysfunction, we treated endothelial cells with KLF2 siRNA." (PMID 34253708, 2021). "Furthermore, we show that genetic or pharmacological activation of KLF2 reverses multiple aspects of endothelial dysfunction." (PMID 34253708, 2021). "Radiation causes endothelial dysfunction, but no study has investigated radiation’s effects on the KLF2 pathway." (PMID 32382091, 2020).
endothelial dysfunction (continued). "In addition, as statins are studied well and proven to attenuate endothelial dysfunction via KLF2 activation, we then performed KLF2 promoter luciferase assays in COS-7 cells and TNFα-induced monocyte adhesion assays to compare the effects of statins (Simvastatin and Atorvastatin) with TSD." (PMID 36362263, 2022). "KLF2 activation (by atorvastatin and tannic acid, a natural KLF2 activator) and KLF2 overexpression (by KLF2 adenovirus) have been proven to significantly reduce patient-serum-induced monocyte adhesion to endothelial cells and have therapeutic potential in limiting endothelial dysfunction." (PMID 35409070, 2022). "The flow-responsive transcription factors KLF2 and KLF4 play an important role in restricting endothelial dysfunction, inflammation, thrombosis, and angiogenesis in response to disturbed flow." (PMID 40362576, 2025). "As shown, KLF2 expression is suppressed by an AGE (advanced glycation end product) and induces endothelial dysfunction." (PMID 35203463, 2022). "Mechanically, IRF2BP2 binds to KLF2 and up-regulates KLF2 expression, resulting in HUVECs protection against ox-LDL-induced inflammation, endothelial-to-mesenchymal transition, and endothelial dysfunction." (PMID 35203463, 2022). "We also observed that adenovirus mediated KLF2 overexpression or atorvastatin reversed COVID-19-patient-serum-induced monocyte adhesion to endothelial cells, suggesting that pharmacological activation of KLF2 could be a viable strategy of ameliorating endothelial dysfunction in COVID-19." (PMID 34253708, 2021). "Preclinical studies have shown that metformin regulates endotoxemia-induced endothelial dysfunction and inflammation through the AMPK/KLF2 axis, restoring KLF2 levels reduced by LPS and TNF-α stimulation, and inhibiting VCAM1 expression while reducing inflammatory factors like TNF-α and IL-6." (PMID 41373858, 2025). "In addition, miR-92a was found to exacerbate endothelial dysfunction under OS exposure by directly targeting SIRT1, Krüppel-like factor 2 (KLF2) and KLF4 genes." (PMID 31514389, 2019).
gastric cancer (36 papers, 2017 to 2026). A primary or metastatic malignant neoplasm involving the stomach. "In gastric cancer, lncRNA-TINCR caused KLF2 mRNA degradation via SMD thereby regulating gastric cancer cell proliferation and apoptosis." (PMID 32015336, 2020). "sphingosine kinase 2-mediated phosphorylation of Krüppel-like factor 2 (KLF2) triggers the degradation of KLF2 protein in gastric cancer." (PMID 41517663, 2026). "LSD1 recruited by Lnc00673l binds to the promoter regions of LATS2 (large tumor suppressor kinase 2) and KLF2 (Krüppel-like factor 2) and decreases methylation levels, thereby inducing growth arrest and decreased invasion of gastric cancer cells." (PMID 40028036, 2025). "Knockdown of KLF2 expression in two independent KLF2-positive gastric cancer cell lines (GSU and LMSU) was sufficient to significantly decrease plasma cell migration (P = 0.001)." (PMID 34642171, 2022). "DLEU1 contributes to cell proliferation by recruiting LSD1 to epigenetically suppress KLF2 in gastric cancer." (PMID 35619131, 2022). "Both KLF2 H3K27ac promoter levels and gene expression were higher in diffuse compared with intestinal gastric cancers (P < 0.05), with good correlations between promoter signals and gene expression (R = 0.55, P = 0.005)." (PMID 34642171, 2022). "METTL3 induced proliferation, migration, angiogenesis and tumorigenesis via inhibition of ADAMTS9 and modification of YAP1 and KLF2 in gastric cancer." (PMID 36003776, 2022). "The lncRNA TINCR is strongly upregulated in gastric cancer, and promotes the growth of gastric cancer cells by regulating the expression of KLF2." (PMID 33732285, 2021). "Rescue experiments were further conducted to elucidate the biological function of LINC01232/KLF2 axis in the progression of gastric cancer." (PMID 34409953, 2021). "We conducted rescue experiments to further clarify the functions of LINC01232 and KLF2 in the progression of gastric cancer." (PMID 34409953, 2021). "KLF2 negatively regulates energy metabolism of tumor cells and inflammation; thus, miRBART action on KLF2 positively favors gastric cancer cell migration and anchorage-independent growth." (PMID 32582365, 2020). "We found that only miR-BART17-5p directly down-regulated KLF2 and promoted gastric carcinoma cell migration and anchorage-independent growth." (PMID 32075248, 2020). "Liu et al32 showed that HOXA11‐AS expression was up‐regulated in gastric cancer tissues and HOXA11‐AS knockdown decreased gastric cancer cell cycle and inhibited gastric cancer cell invasion, metastasis and migration through regulating β‐catenin and KLF2." (PMID 29761918, 2018). "In GC cells, a previous study found that long non-coding RNA ZFAS1 promoted gastric cancer cells proliferation by epigenetically repressing KLF2 and NKD2 expression." (PMID 29113337, 2017). "In this study, we investigated the expression pattern and relevant clinical features of KLF2 in human gastric cancer and the effect of its alteration on gastric cancer cell biology." (PMID 29245984, 2017). "Currently, there is little known about KLF2’s expression and its potential contribution to gastric cancer formation." (PMID 29245984, 2017). "We further explored the potential mechanism of KLF2 by taking advantage of the stable KLF2 human gastric cancer cell lines." (PMID 29245984, 2017). "Various cell experiments showed that ectopic KLF2 expression suppressed the proliferation, migration and invasion of gastric cancer cells." (PMID 29245984, 2017). "In conclusion, we found that expression of KLF2 was relatively high in normal gastric epithelium, and was often downregulated in gastric cancer cell lines and tissues." (PMID 29245984, 2017). "By contrast, we discovered that KLF2’s expression level was substantially lower in both gastric cancer cell lines and human tumor specimens." (PMID 29245984, 2017). "Mechanistically, ZFAS1 was found to promote gastric cancer cell proliferation by inhibiting KLF2 and NKD2 expression." (PMID 28938617, 2017).
gastric cancer (continued). "Further investigations determined that tumor suppressors NKD2 and KLF2 are novel ZFAS1 targets in gastric cancer cells." (PMID 27246976, 2017). "Next, we systematically analyzed KLF2 expression in 80 human gastric cancer tissue samples on the tissue microarray by IHC staining." (PMID 29245984, 2017). "The results showed that KLF2 was downregulated in human gastric cancer and directly correlated with patient survival rate." (PMID 29245984, 2017). "To determine the expression of KLF2 in human gastric cancer, we first analyzed the gene expression profiles in GC found in The Cancer Genome Atlas (TCGA) database." (PMID 29245984, 2017). "Furthermore, lncRNA DLEU1 can promote gastric cancer cell proliferation by upregulating KLF2 by recruiting LSD1 to the KLF2 promoter region." (PMID 37781524, 2023). "To test this hypothesis, we compared KLF2 expression between diffuse- and intestinal-subtype gastric cancers across the various cell states." (PMID 34642171, 2022). "In agreement with our results in primary gastric cancers, KLF2pos xenografts had high expression of plasma cell markers IRF4 and SLAMF7 in the humanized mice only, reflecting increased plasma cell recruitment associated with KLF2." (PMID 34642171, 2022). "To further demonstrate a causative role for epithelial KLF2 in plasma cell recruitment, we then performed in vitro migration assays using plasma cells derived from peripheral blood mononuclear cells (PBMC) or KMS-11 (a multiple myeloma cell line) cocultured with KLF2-positive gastric cancer cells." (PMID 34642171, 2022). "LINC01232 exerts oncogenic activities in gastric cancer via inhibition of KLF2, and therefore, the knockdown of KLF2 could reverse the regulatory effect of LINC01232 in the proliferative ability of gastric cancer cells." (PMID 34409953, 2021). "In addition, knockdown of STAU1 or overexpression of KLF2 in gastric cancer cells increased expression levels of cyclin-dependent kinases and reduced cell proliferation." (PMID 34633481, 2021). "Meanwhile, the knockdown of KLF2 could reverse the regulatory effect of LINC01232 in the proliferative ability of gastric cancer cells." (PMID 34409953, 2021). "To determine whether ZFAS1 repressed NKD2 and KLF2 expression via interacting with EZH2 or LSD1 in gastric cancer cells, we evaluated their expression after knockdown of EZH2 and LSD1 in gastric cancer cells." (PMID 27246976, 2017). "Thus, our study defines KLF2 as a tumor suppressor in human gastric cancer that regulates PTEN expression to repress downstream AKT-mTOR signaling." (PMID 29245984, 2017). "Therefore, in this study we investigated the effects of LINC01232 targeting KLF2 on the proliferation of gastric cancer cells, which may potentially be used as a therapeutic target for the treatment of gastric cancer in future." (PMID 34409953, 2021). "Therefore, we also intended to figure out whether FBW7 negatively regulates tumor metastasis through targeting c-Jun or KLF-2 in gastric cancer settings." (PMID 30177679, 2018). "Moreover, it is still obscure whether and, if so, how KLF2 is involved in the tumorigenesis of gastric cancer." (PMID 29245984, 2017). "In gastric cancer, it enhances malignancy by upregulating oncogenes such as MYC and suppressing tumor suppressors like KLF2." (PMID 41517663, 2026). "The PRC2 complex that establishes repressive H3K27me3 marks has been shown recruited on the Kruppel Like Factor 2 (KLF2) and CDH1 promoters in gastric cancer cells." (PMID 33803458, 2021). "In gastric cancer cell lines (SGC7901 and BGC823), upregulated TINCR lncRNA forms a ribonucleoprotein complex with STAU1, UPF1, and KLF2 mRNA that promotes SMD of KLF2 transcripts." (PMID 34633481, 2021). "A similar effect was observed in gastric cancer cells and tumors in which STAU1-mediated degradation of the KLF2 transcription factor, promotes in vitro and in vivo metastasis." (PMID 34633481, 2021).
gastric cancer (continued). "In a similar way, lncRNA-TINCR can degrade KLF2 mRNA expression through SMD, and promote cell cycle progression, and tumorigenicity subsequently in gastric cancer cells." (PMID 32015336, 2020). "The proposed target genes also seem quite different for different cancers, e.g. TIF1 (gastric cancer), ATG7 (hepatocarcinoma), and KLF2 (ovarian cancer)." (PMID 28418884, 2017). "Furthermore, ZFAS1 expression is also overexpressed in gastric cancer, and its increased level is correlated with a shorter survival and poor prognosis and promotes the proliferation of gastric cancer cells by epigenetically repressing the KLF2 and NKD2 expression levels." (PMID 28154416, 2017). "We functionally explored this possibility in “humanized mice,” by xenografting human-derived diffuse-type gastric cancer cell lines that were KLF2 positive and negative." (PMID 34642171, 2022). "LncRNA TINCR could bind to STAU1, influenced KLF2 mRNA stability, and regulated CDKN1A/p21 expression, thereby affecting proliferation and apoptosis of gastric cancer cells." (PMID 34234860, 2021). "Reduced levels of the transcription factor KLF2 decreases mRNA expression of two important target genes, cyclin-dependent kinase CDKN1A/P21 and CDKN2B/P15 (inhibitors of cell cycle checkpoints and cell proliferation) that promote gastric cancer cell growth." (PMID 34633481, 2021). "However, since LMP1 expression is abrogated in EBV-positive gastric cancer, the main effect of miR-BART17-5p occurs on the transcription factor Kruppel-like factor 2 (KLF2)." (PMID 32582365, 2020). "With regards to function, ZFAS1 has been shown to regulate cell proliferation and migration of ovarian cancer by targeting miR-150-5p, whereas, in gastric cancer, ZFAS1 was demonstrated to accelerate cell proliferation via repressing the expression of KLF2 and NKD2." (PMID 29416676, 2018). "In this study, we also found that KLF2 can function as tumor suppressor and its' expression could be suppressed by ZFAS1 through recruiting EZH2 and LSD1 to its promoter region in gastric cancer cells." (PMID 27246976, 2017). "To further determine whether KLF2 and NKD2 is involved in the ZFAS1 induced promotion of gastric cancer cells proliferation, we detected their expression in 20 pairs gastric cancer and normal tissues and found that their expression are both decreased in gastric cancer tissues." (PMID 27246976, 2017). "Experiments in vivo also showed that knockdown of ZFAS1 inhibited the tumorigenic ability of gastric cancer cells, and mechanistic experiments validated that ZFAS1 could promote the proliferation of gastric cancer cells by inhibiting the expression of KLF2 and NKD2." (PMID 28938617, 2017). "Moreover, we conducted rescue assays to determine whether KLF2 and NKD2 involved in ZFAS1 contributions to gastric cancer cell proliferation." (PMID 27246976, 2017).